IFI30 (IFI30 lysosomal thiol reductase)
Diseases named in the same sentence as IFI30 in open-access papers (continued):
Sharing a sentence is not in itself a finding about the gene and the disease.
glioma (continued). "The current study suggests that IFI30 could be a potential therapeutic target for glioma." (PMID 37408388, 2023). "However, the role of IFI30 in human glioma is still poorly understood." (PMID 37408388, 2023). "Furthermore, we conducted univariable and multivariable analyses to confirm whether IFI30 expression was an independent prognostic biomarker for gliomas." (PMID 32969157, 2020). "Finally, we evaluated the correlation of IFI30 expression with some important immune checkpoints, which could reflect the immune microenvironment of gliomas with different IFI30 expression levels." (PMID 32969157, 2020). "A recent study carried out an analysis on glioma patients from the Chinese Glioma Genome Atlas (CGGA) and The Cancer Genome Atlas (TCGA) cohorts and identified IFI30 as a promising prognostic gene in glioma among ISGs." (PMID 37408388, 2023). "In this study, we investigated the biological function of IFI30 in both normal and TMZ‐treated glioma cells." (PMID 37408388, 2023). "Overall, IFI30 enhanced TMZ resistance and decreased the cytotoxic effect of TMZ therapy on glioma cells." (PMID 37408388, 2023). "We further demonstrated that the EGFR/AKT/GSK3β/β‐catenin axis played a role in IFI30‐promoted the EMT‐like phenotype, which is a well‐recognized mechanism in the diffuse infiltration of glioma cells." (PMID 37408388, 2023). "Clinical study has confirmed that IFI30 expression was upregulated in GBM tissues and was a significantly poor prognostic marker of patients with glioma." (PMID 35436915, 2022). "In the gliomas that were stratified on the basis of the IDH and 1p/19q status, the IFI30 expression level was the highest in the IDH wild‐type (IDH‐wt) group, both in the lower‐grade gliomas (LGG, grade II and III) and GBM (C for CGGA, F for TCGA)." (PMID 32969157, 2020). "IFI30 expression was significantly increased along with the grade of the tumour and was the highest in glioblastomas (GBM, glioma grade IV)." (PMID 32969157, 2020). "In this study, we collected the mRNA sequencing data of 921 glioma samples from the CGGA and TCGA databases and analysed the expression pattern, prognostic value, and potential biological significance of the IFI30 gene." (PMID 32969157, 2020). "We have observed heterozygous amplification of IFI30 and PTBP1, suggesting that their CNV may have the potential to modify the immune infiltration status of glioma patients to a certain degree." (PMID 41438761, 2025). "Our findings revealed a positive correlation between the expression levels of APOC1 and IFI30 in glioma and the majority of cytokines, while a negative correlation was observed between their methylation status and these cytokines." (PMID 41438761, 2025). "Thus, we conclude that IFI30 is a regulator of the EMT‐like process and acts not only as a prognostic marker but also as a novel biomarker of the response to TMZ in glioma." (PMID 37408388, 2023). "The present study suggests that IFI30 is a regulator of the EMT‐like phenotype and acts not only as a prognostic marker but also as a potential therapeutic target for temozolomide‐resistant glioma." (PMID 37408388, 2023). "In this study, we found that the mRNA expression of IFI30 in glioma tissues was significantly higher than that in normal brain tissues (NBTs) using RNA‐seq data from the GTEx and TCGA datasets." (PMID 37408388, 2023). "IFI30‐mediated EGFR/AKT/GSK3β/β‐catenin signaling not only promotes the epithelial–mesenchymal transition‐like phenotype by upregulating the expression of Slug, but also subsequently enhanced invasion and chemoresistance of glioma cells." (PMID 37408388, 2023). "Taken together, these results suggest that IFI30‐mediated EGFR/AKT/GSK3β/β‐catenin signaling not only promotes the EMT‐like phenotype by up‐regulating the expression of Slug, but also subsequently enhanced invasion and chemoresistance of glioma cells." (PMID 37408388, 2023).
breast carcinoma (16 papers, 2013 to 2025). "Histopathologic analyses of 82 breast cancer specimens revealed that higher IFI30 expression was significantly associated with distant tumor metastasis." (PMID 34400904, 2021). "It is noteworthy that a study reported that deficiency of IFI30 was associated with poor disease-free survival in breast cancer patients 23, while we obtained different results by bioinformatics and clinical case validation." (PMID 34400904, 2021). "In conclusion, the present study demonstrated that IFI30 was highly expressed in breast cancer tissues and was associated with poor patient prognosis." (PMID 34400904, 2021). "We further examined IFI30 protein expression levels in clinical breast cancer samples and obtained the same results, confirming that IFI30 was highly expressed in breast cancer tissues and was associated with poor prognosis." (PMID 34400904, 2021). "The results above suggested that high expression of IFI30 mRNA was associated with poor prognosis of breast cancer." (PMID 34400904, 2021). "Intriguingly, however, IFI30 RNA expression is associated with better patient survival in breast cancer and diffuse large B cell lymphomas (DLBCL) while GPB1 RNA is associated with better patient survival in melanoma but poorer prognosis in human glioblastoma." (PMID 32265897, 2020). "We reported variant peptide from protein IFI30 in breast cancer which was confirmed expressed and presented in two samples with mass spectrometry data support." (PMID 33363023, 2020). "One of the up-regulated genes in this set is IFI30, interferon gamma-inducible protein 30, which is linked to breast cancer." (PMID 24376830, 2013). "A representative example being gamma interferon-inducible lysosomal thiol reductase (GILT/IFI30) whose low expression has been associated with a higher Ki67 proliferation index and poorer survival in breast cancer." (PMID 36998085, 2023). "Immunohistochemistry results in 82 cases of breast cancer tissue wax blocks suggested that IFI30 was high expressed in breast cancer." (PMID 34400904, 2021). "In the present study, bioinformatics analysis of TCGA database and CPTAC database indicated that there was a high expression of both mRNA and protein of IFI30 in breast cancer clinical samples." (PMID 34400904, 2021). "Next, according to TCGA database, the correlation between IFI30 mRNA expression and prognosis of breast cancer was analyzed." (PMID 34400904, 2021). "We used lentivirus infection method to construct a stable IFI30 knockdown cell line, and detected the effect of IFI30 in breast cancer cells." (PMID 34400904, 2021). "Then we detected the expression of IFI30 in clinical samples of breast cancer patients, and analyzed the relationship between IFI30 and the prognosis of breast cancer patients." (PMID 34400904, 2021). "Nude mice tumor bearing experiment was performed to investigate the effect of IFI30 on breast cancer cells in vivo." (PMID 34400904, 2021). "Our previous results in vitro confirmed that knockdown of IFI30 inhibited the proliferation, migration and invasion of breast cancer cells, and to further confirm the role of IFI30 in vivo, we performed subcutaneous tumor bearing experiments in nude mice." (PMID 34400904, 2021). "We found that IFI30 protein expression in breast cancer was significantly higher than that in normal tissues, especially in triple negative breast cancer." (PMID 34400904, 2021). "TCGA and CPTAC database analysis showed that IFI30 mRNA and protein were highly expressed in breast cancer tissues, and the high expression of IFI30 mRNA was associated with poor outcome of patients." (PMID 34400904, 2021). "Immunohistochemistry results were further analyzed and the results obtained showed that high IFI30 expression correlated with breast cancer metastasis and poor OS and DMFS in breast cancer patients." (PMID 34400904, 2021).
breast carcinoma (continued). "In order to further understand the expression of IFI30 mRNA in different molecular types of breast cancer, we continued to analyze according to the molecular typing of breast cancer in TCGA database." (PMID 34400904, 2021). "Protein is the executor of gene's final function; therefore, we used bioinformatics to analyze the expression of IFI30 protein in breast cancer." (PMID 34400904, 2021). "The role of IFI30 in breast cancer and clear cell renal carcinoma remains controversial." (PMID 40186402, 2025). "The knockdown of IFI30 could inhibit the proliferation, migration and invasion of breast cancer cells and significantly inhibit tumor growth in vivo." (PMID 34400904, 2021). "Moreover, knockdown of IFI30 inhibited the proliferation, migration and invasion of breast cancer cells and significantly inhibited tumor growth in vivo." (PMID 34400904, 2021). "In addition, lentivirus mediated small hairpin RNA (shRNA) was used to knock down IFI30 gene to explore its function in breast cancer cells." (PMID 34400904, 2021). "Discussion: As a result, we suggested that IFI30 might play a key role in the initiation and progression of human breast cancer and might be a new therapeutic target in breast cancer." (PMID 34400904, 2021). "In this study, the effect of IFI30 on breast cancer was investigated." (PMID 34400904, 2021). "Knockdown of IFI30 could significantly inhibit the proliferation, colony formation, migration and invasion of breast cancer cells." (PMID 34400904, 2021). "IFI30 may play a key role in the initiation and progression of human breast cancer and hold promise as a new therapeutic target in breast cancer." (PMID 34400904, 2021). "We reported that RE neoantigen might play a pivotal role in breast cancer and IFI30 might be a potential as therapeutic target." (PMID 33363023, 2020). "However, the role of IFI30 in breast cancer is still poorly understood." (PMID 34400904, 2021). "It suggested that IFI30 might relate to the development, metastasis and invasion in breast cancer." (PMID 34400904, 2021). "Our results revealed that IFI30 may promote tumorigenesis in breast cancer cells." (PMID 34400904, 2021). "As IFI30 could affect the tumorigenesis and development of cancers, we analyzed TCGA database to detect the expression of IFI30 mRNA in breast cancer tissues and found that the expression level of IFI30 mRNA in breast cancer tissues was higher than that in normal tissues obviously." (PMID 34400904, 2021). "The results showed that IFI30 mRNA is all highly expressed in basal like, human epidermal growth factor receptor 2 (HER-2) positive, Luminal A and Luminal B molecular types of breast cancer." (PMID 34400904, 2021). "In the selected key specific DEGs for Her2-subtype breast cancer, the expression of IL21R, IFI30, PI15, FAM189A2, and MYZAP were significantly correlated with the prognostic survival of the patients." (PMID 33644115, 2021). "IFI30 protein expression was higher especially in triple negative breast cancer and HER-2 positive breast cancer." (PMID 34400904, 2021). "Increased accumulation of LC3-II and p62 suggested impaired autophagy in IFI30 stable knockdown MDA-MB-231 and SK-BR-3 breast cancer cells." (PMID 34400904, 2021). "In brief, the data in Her2-subtype breast cancer suggest that IL21R, IFI30, and MYZAP may be involved in the tumorigenesis to improve OS of patients with Her2-subtype breast cancer." (PMID 33644115, 2021). "According to the bioinformatics prediction, we detected the expression of IFI30 protein in clinical breast cancer samples as well as corresponding non-tumor normal tissues to determine the role of IFI30 in breast cancer." (PMID 34400904, 2021). "We performed Western blot assay on fresh samples from 60 pairs of breast and adjacent noncancerous tissues and found that IFI30 protein was highly expressed in breast cancer tissues." (PMID 34400904, 2021).
breast carcinoma (continued). "IL21R, IFI30, PI15, and FAM189A2 may be involved in recurrence of Her2-subtype breast cancer IFI30, PI15, FAM189A2, and MYZAP can be used as the specific prognostic markers for Her2-subtype breast cancer." (PMID 33644115, 2021). "Our analysis showed that IFI30 were specifically upregulated and this high expression predicted high RFS and OS (p < 0.05) in Her2-subtype breast cancer, while high IFI30 expression predicted low RFS and OS (p < 0.05) in all breast cancer." (PMID 33644115, 2021). "Thus, the elevated expression of IFI30 might improve the prognosis of patients with DLBCL and breast cancer." (PMID 37408388, 2023). "Consequently, we generated stable IFI30 knockdown cell lines using lentiviral infection in triple negative breast cancer MDA-MB-231 cells and HER-2 positive breast cancer SK-BR-3 cells." (PMID 34400904, 2021).
prostate carcinoma (9 papers, 2014 to 2025). A carcinoma that arises from epithelial cells of the prostate gland. "In prostate cancer, IFI30 expression has been confirmed to be associated with its progression, which is consistent with our results." (PMID 37065491, 2023).
COVID-19 (7 papers, 2020 to 2024). A disease caused by infection with severe acute respiratory syndrome coronavirus 2. "We observed that genes encoding HLA class 1 (HLA-E, PSMA-6, TAP1, IFI30) were enriched in COVID-19 ECs." (PMID 37029220, 2023). "The Mon IFI30 subtype is characterized by a specific gene expression profile clearly indicating that severe Delta variant COVID-19 leads to specific immune shifts." (PMID 36230912, 2022). "Previously, we showed that the proinflammatory subtype of monocytes (Mon IFI30) accompanies severe Delta COVID-19, and this population yields high expression of IFI30, C15orf48, CXCL8, CSTB, and SPP1 genes." (PMID 39712003, 2024). "Together, we identified groups of open chromatin regions that are specific for the Mon IFI30 cell type that accompanies severe/critical Delta COVID-19." (PMID 39712003, 2024). "Here, we characterized the cis-regulatory level Mon IFI30 cell subpopulation that we previously identified using scRNA-seq in the PBMC of patients with severe/critical Delta COVID-19." (PMID 39712003, 2024). "Our analysis revealed that PBMC from infants with acute Omicron and pre-Omicron COVID-19 demonstrated elevated chromatin accessibility of Mon IFI30 marker genes." (PMID 39712003, 2024). "Moreover, we identified that more than half of the Mon IFI30 marker peaks were shared with monocytes from infants affected with COVID-19, and BACH1, NFE2L2, FOS, and FOSL2 are the master regulators of the cell state." (PMID 39712003, 2024). "Importantly, these results predict a novel association between regulatory factors controlling transcription and target expression markers of the proinflammatory Mon IFI30 cell state that accompanies the severe form of Delta COVID-19." (PMID 39712003, 2024). "Severe/critical Delta COVID-19 is accompanied by depletion of classical CD14 monocytes and enrichment of Mon IFI30." (PMID 39712003, 2024). "For Mon IFI30, we also found MAFB and MAF as highly expressed and previous studies proposed their role for control of macrophage checkpoints in COVID-19 severity and as a marker for progression." (PMID 36230912, 2022). "In addition, recoded key antiviral and immune-related proteins such as IFI30 and GBP1 recoded by missense editing was observed as an essential component of RNA editing in response to COVID-19 vaccines." (PMID 39308856, 2024). "In addition, IFI30 was specifically upregulated in monocytes during HIV-1 infection, whereas SLAMF7 and IFIT3 were upregulated in plasmablasts and T cells from COVID-19 patients respectively." (PMID 36992700, 2023). "The missense RNA editing level of IFI30 (IFI30:chr19:18177741, p.T223A) was significantly up-regulated, whereas the GBP1 missense editing (GBP1:chr1:89057096, p.S305G) was significantly down-regulated, with the expression of both genes increased during COVID-19 vaccines." (PMID 39308856, 2024).
glioblastoma (6 papers, 2014 to 2025). The most malignant astrocytic tumor (WHO grade IV). "Moreover, the synergistic effect of the IFI30 expression level and M2 macrophages indicated a poor prognosis for patients, which implies that IFI30 may alter the immune microenvironment of glioblastoma by influencing M2 macrophages." (PMID 39925804, 2025). "Pan-cancer analyses and glioblastoma multiforme (GBM) investigations collectively underscore IFI30's potential as a TME modulator, particularly in its interaction with M2-macrophages." (PMID 39925804, 2025).
autoimmune disease (5 papers, 2010 to 2024). A disorder resulting from loss of function or tissue destruction of an organ or multiple organs, arising from humoral or cellular immune responses of the individual to their own tissue constituents. "IFI30 has been implicated in the pathogenesis of some autoimmune diseases, and genetic polymorphisms of ERAP2 and its paralog ERAP1 are associated with increased susceptibility to autoimmune/chronic inflammatory disorders." (PMID 35954309, 2022). "Studies have shown that IFI30 plays a substantial part in shaping the tissue-restricted autoantigens of CD4+ T cells in mediating autoimmune diseases and anti-tumor immunity." (PMID 37991414, 2024).
Autoimmunity (4 papers, 2013 to 2025). The occurrence of an immune reaction against the organism's own cells or tissues. "IFI30 gene encodes GILT enzyme which is expressed in antigen-presenting cells and plays a role in MHC class II-restricted antigen processing and regulates CD4 + T cell-mediated autoimmunity." (PMID 39992598, 2025). "Previous studies similarly demonstrated the ability of IFI30 either to affect the redox of cells, leading to the regulation of autophagy, cell activation and proliferation, or to modulate the T-cell tolerance and thus bridge the potentially arising autoimmunity." (PMID 37215115, 2023).
Obesity (4 papers, 2020 to 2025). Accumulation of substantial excess body fat. "Differential gene expression revealed that genes associated with innate immune responses (LYZ), antigen processing and presentation (HLA-DRB1, HLA-DRB5, IFI30), as well as cell signaling and migration (VIM, RGS1, NCF) were upregulated in the HBC subset with pregravid obesity." (PMID 39872537, 2024). "Additionally, a direct correlation between BMI and gene expression was observed for AGER, ANGPT2, CD68, IFI30, NOTCH3 and SPP1, whereas an inverse correlation was achieved for DLL4, PLIN, PNPLA2 and VEGF (genes that were down-regulated due to obesity)." (PMID 33022994, 2020).
diabetes (3 papers, 2010 to 2025). "IFI30 genetic variants are associated with plasma C-reactive protein levels, hyperglycemia, and diabetes." (PMID 41356597, 2025).
gastric cancer (3 papers, 2020 to 2023). A primary or metastatic malignant neoplasm involving the stomach. "We also assessed the survival associations of IFI44 and IFI30 expressions using the gene expression data of gastric cancer patients registered in the Gene Expression Omnibus (GEO)." (PMID 33257699, 2020). "When the expression of IFI30 in GC cells was attenuated, a significant decrease in migration and invasive ability was observed, suggesting that the genes involved in the model construction are a major risk factor for gastric cancer, regardless of the model itself." (PMID 37215115, 2023).
Hypertension (2 papers, 2022 to 2023). The presence of chronic increased pressure in the systemic arterial system. "Among the ISGs, Ifi30, derived from DEGs of monocytes and macrophages, has been correlated with hypertension in patients with abdominal aortic aneurism or intracranial aneurism." (PMID 38045685, 2023).
lung adenocarcinoma (2 papers, 2023 to 2025). A carcinoma that arises from the lung and is characterized by the presence of malignant glandular epithelial cells. "In a similar manner, expression of C2, IFI30 and TUBB4 was negatively associated with the disease outcome in lung adenocarcinoma compared to other carcinomas." (PMID 37784035, 2023).